CX3CR1 (C-X3-C motif chemokine receptor 1)
Diseases named in the same sentence as CX3CR1 in open-access papers (continued):
Sharing a sentence is not in itself a finding about the gene and the disease.
ovarian carcinoma (continued). "The detailed relationship between CX3CR1 and epithelial ovarian cancer survival prognosis under different clinicopathological characteristics was analyzed by using Kaplan–Meier plotter database." (PMID 38241595, 2024). "The TIMER database was applied to assess the correction between the expression of CX3CR1 gene and lymphocytes abundance in epithelial ovarian cancer." (PMID 38241595, 2024). "The potential prognostic value of CX3CR1 for epithelial ovarian cancer was confirmed in Kaplan–Meier plotter database." (PMID 38241595, 2024). "The expression level of CX3CR1 gene and protein in normal ovaries and epithelial ovarian cancer by applying available web databases in HPA, GEPIA2, Sangerbox, and TISIDB, and CX3CR1 mutation data were analysis in cBioPortal." (PMID 38241595, 2024). "Particularly, CX3CR1 expressed higher in epithelial ovarian cancer than that in normal ovarian tissue." (PMID 38241595, 2024). "Our studies indicate that the impairment of CX3CR1 can synergize with dsDNA-damaging agents to eliminate ovarian cancer cells." (PMID 39594684, 2024). "Among the distinct immune subtypes (C1–C6) of epithelial ovarian cancer, C3 (inflammatory type) expressed the highest level of CX3CR1 than other immune subtypes." (PMID 38241595, 2024). "We previously reported that elevated CX3CR1 expression in ovarian carcinoma contributes to the dsDNA repair process and its reduction sensitizes cells to DNA-damaging therapeutic modalities, including X-ray radiation." (PMID 39594684, 2024). "The TISIDB database also verified that CX3CR1 gene expression strongly concerned in lymphocytes infiltration for epithelial ovarian cancer, especially macrophages (R = 0.46), MDSC (R = 0.47), and activated B cells (R = 0.66)." (PMID 38241595, 2024). "Numerous online databases, including GEPIA, cBioPortal, TISIDB (an integrated repository portal for tumor-immune system interactions), and TIMER, were retrospectively explored to verify the role of CX3CR1 in epithelial ovarian cancer." (PMID 38241595, 2024). "The increased CX3CR1 expression related to favorable prognosis of epithelial ovarian cancer, which robustly suggested that CX3CR1 can be applied as a promising prognostic biomarker for epithelial ovarian cancer." (PMID 38241595, 2024). "The findings showed that CX3CR1 expression was higher in epithelial ovarian cancer than in normal ovarian tissue and other tumors, and closely related to immune microenvironment regulation." (PMID 38241595, 2024). "Higher level of CX3CR1 expression predicted better prognosis of epithelial ovarian cancer and early stage." (PMID 38241595, 2024). "Correlation of CX3CR1 mRNA expression and clinical prognosis in epithelial ovarian cancer with different clinicopathological factors by Kaplan–Meier plotter." (PMID 38241595, 2024). "Follow up studies in ovarian cancer cell lines showed that hypoxia upregulated CX3CR1, and these cells responded to CX3CL1 in cell spheroid invasion assays." (PMID 36118530, 2022). "In ovarian cancer cells, CX3CR1 was upregulated in a course of hypoxia-mediated regulation of hypoxia-inducible factor-1α (HIF-1α)." (PMID 36246557, 2022). "In ovarian cancer, CX3CR1 is generally overexpressed, and the degree of overexpression correlates with cancer stage 136." (PMID 36118530, 2022). "CX3CR1 was also found to be expressed in more than 64% of metastatic ovarian cancer specimens, and it promotes ovarian cancer cell adhesion to the mesothelial monolayer and proliferation in a CX3CL1-dependent manner." (PMID 36685881, 2022). "Therefore, it is very important to explore whether the CX3CL1/CX3CR1 gene polymorphism is significantly related to the clinical treatment of ovarian cancer and to screen alleles related to clinical efficacy for the individualized treatment of ovarian cancer." (PMID 36685881, 2022).
ovarian carcinoma (continued). "Based on this, in-depth exploration of the function and mechanism of the CX3CL1/CX3CR1 axis in ovarian cancer will provide a strong theoretical basis for the targeted therapy of ovarian cancer." (PMID 36685881, 2022). "Meanwhile, the CX3CL1/CX3CR1 coding region was found to have SNPs with various amino acid substitutions, such as the T280M SNP and V249I SNP, which would affect their expression, function and activity and may cause platinum resistance in ovarian cancer patients." (PMID 36685881, 2022). "In support of this notion, CX3CR1 has been identified in genome-wide siRNA screens aiming to identify regulators of genome stability and its knockdown sensitizes ovarian cancer xenografts to DNA-damaging ionizing radiation." (PMID 33810010, 2021). "Further, the fractalkine receptor (CX3CR1) expressed by ovarian cancer cells has also been demonstrated to mediate ovarian cancer cell adhesion to mesothelium by interacting with its ligand CXCL1 present on the surface of mesothelial cells’ surface." (PMID 30909510, 2019). "Our previous studies demonstrated that interaction of CX3CR1 expressed in ovarian carcinoma cells with membrane-tethered CX3CL1 expressed in peritoneal mesothelial cells mediates peritoneal adhesion of disseminating cells." (PMID 29712888, 2018). "This study identifies CX3CR1 as a novel potential target for sensitization of ovarian carcinoma to DNA damage therapies and reduction of peritoneal carcinomatosis." (PMID 29712888, 2018). "In agreement with data suggesting significant and strong co-expression of CX3CR1 with GPR65 and FFAR4 in specimens, western blot confirmed robust downregulation of GPR65 and FFAR4 in ovarian carcinoma cell lines transfected with CX3CR1-specific siRNAs." (PMID 29712888, 2018). "In ovarian cancer, high expression of the fractalkine receptor CX3CR1 correlated with significantly shorter survival in post-menopausal patients with advanced disease." (PMID 29157300, 2017). "In a mouse model of ovarian cancer, CX3CR1-expressing myeloid cells promoted immunosuppression through inhibition of T-cell activity by IL-10, suggesting that CD11b+CX3CR1+ cells function as MDSCs." (PMID 29190915, 2017). "The chemokine (C-X3-C motif) receptor 1 (CX3CR1) is expressed by ovarian cancer cells and was shown to mediate in vitro tumour cell adhesion to mesothelial cells by interacting with mesothelial chemokine (C-X3-C motif) ligand 1 (CX3CL1)." (PMID 27074785, 2016). "This is opposite from the ovarian carcinoma, where both CX3CR1 and CX3CL1 are expressed by the ovarian carcinoma cells." (PMID 26633537, 2015). "Although expression of CX3CR1 in normal and pathologic ovarian surface epithelium and ovarian carcinoma as well as normal fallopian tube epithelium has been tested, the expression status of this receptor in fallopian carcinoma is not known." (PMID 26633537, 2015). "Targeting CX3CR1-dependent TAM functions may represent a therapeutic strategy for limiting peritoneal dissemination in ovarian cancer." (PMID 42279436, 2026). "Previous work has mainly shown that the receptor for CX3CL1, CX3CR1, may promote proliferation, migration, and adhesion of ovarian cancer cells and thus promote tumour spread." (PMID 39862711, 2025). "Furthermore, the CX3CR1 expression level correlation with prognostic value in ovarian cancer by analyzing the data from GEPIA and Kaplan–Meier plotter databases." (PMID 38241595, 2024). "And in epithelial ovarian cancer, amplification was the main change for CX3CR1." (PMID 38241595, 2024). "Furthermore, TISIDB database visualized that CX3CR1 was highest expressed in stage IV epithelial ovarian cancer and lowest in stage I (P = .00476)." (PMID 38241595, 2024). "The Human Protein Atlas, gene expression profiling interactive analysis, and TISIDB (an integrated repository portal for tumor-immune system interactions) database showed that CX3CR1 expressed higher in epithelial ovarian cancer than that in normal ovarian tissue." (PMID 38241595, 2024).
ovarian carcinoma (continued). "The expression of the CX3CR1 in epithelial ovarian cancer was higher than that in normal ovaries." (PMID 38241595, 2024). "We hypothesized that the induction of HRD via the inhibition of CX3CR1 could sensitize ovarian cancer cells to PARPis." (PMID 39594684, 2024). "Therefore, this comprehensive and in-depth study provided new insights into the potential immunomodulatory role of CX3CR1 in the epithelial ovarian cancer microenvironment and suggested it as a biomarker for cancer prognosis." (PMID 38241595, 2024). "In this study, our approach aimed to investigate whether the inhibition of CX3CR1, which leads to reduced HR efficiency, could synergize with PARPis in eliminating ovarian cancer cells." (PMID 39594684, 2024). "Besides, this study also showed that immune cells and multitudinous immunomodulators in epithelial ovarian cancer were correlated with expression level of CX3CR1." (PMID 38241595, 2024). "Here, we investigated the relationship between CX3CL1 and CX3CR1 genotypes and the clinical efficacy of carboplatin in ovarian cancer, thereby clarifying the unidentified genetic factors that influence the efficacy of carboplatin in ovarian cancer." (PMID 36685881, 2022). "At present, studies have reported that the CX3CL1/CX3CR1 biological axis can affect the drug resistance of ovarian cancer cells by mediating changes in the levels of inflammatory factors and cytokines, thereby maintaining the sensitivity of tumor cells to platinum drugs." (PMID 36685881, 2022). "We hypothesized that these mechanisms could play a role in CX3CR1-dependent downregulation of RAD50 in ovarian cancer cells." (PMID 29712888, 2018). "Furthermore, our studies indicated that the CX3CL1/CX3CR1 axis supported ovarian carcinoma cell adhesion and proliferation, further suggesting its potential pivotal role in development and progression of ovarian carcinoma metastasis." (PMID 24384839, 2013). "Therefore, CX3CR1 involved in reshaping the immune microenvironment for epithelial ovarian cancer and maybe a potential immunotherapy target and prognostic marker for ovarian cancer." (PMID 38241595, 2024). "CX3CR1 is a chemokine receptor that plays a role in reshaping the immune microenvironment of epithelial ovarian cancer, and CX3CR1 maybe a potential immunotherapy target and prognostic marker for ovarian cancer, which were worthy for further and deeply study." (PMID 38241595, 2024). "Such an approach may be optimally tailored by choosing a chemokine ligand and receptor matching pair that overlaps with physiological chemokine ligand expression in specific tumours e.g. using CX3CL1/CX3CR1 matching in ovarian cancer or CCL-19/CCR7 matching in breast cancer." (PMID 29157300, 2017). "For instance, CX3CR1 was significantly correlated with CCL2/3 and (R = 0.34, P < 1.03e−09) and CX3CL1 (R = 0.18, P < .0015) in epithelial ovarian cancer." (PMID 38241595, 2024). "The expression of CX3CR1 was also significantly related to chemokine receptors, including CXCR2 (R = 0.54, P < 2.2e−16) and CCR5 (R = 0.43, P < 2.2e−16) in epithelial ovarian cancer." (PMID 38241595, 2024). "To test this premise, we combined a CX3CR1 inhibitor with several inhibitors of PARP and investigated the efficacy of these combinations in ovarian cancer cell lines and xenograft models." (PMID 39594684, 2024). "CX3CR1 was dim correlated with immunostimulators in epithelial ovarian cancer, such as CD86 (R = 0.49, P < 2.2e−16) was the most closely related to CX3CR1." (PMID 38241595, 2024). "Groups of adult female Cx3cr1+/GFP and Cx3cr1GFP/GFP mice were either administered normal saline or left untreated and, at 7 days thereafter, were inoculated i.p. with ID8 mouse ovarian cancer cells." (PMID 37345662, 2023). "Patterns of CX3CR1 and CX3CL1 expression in normal epithelium of ovary and fallopian tube, fallopian epithelium with chronic inflammation, ovarian carcinoma, and fallopian adenocarcinoma." (PMID 26633537, 2015).
ovarian carcinoma (continued). "The relationship between CX3CR1 and genomic biomarkers in epithelial ovarian cancer has been calculated, but there was no positive correlation." (PMID 38241595, 2024). "However, the immune functional and prognostic value of CX3CR1 in epithelial ovarian cancer has not been clarified." (PMID 38241595, 2024). "Our data suggest that, unlike in the ovarian carcinoma, autocrine activation of CX3CR1 by CX3CL1 in fallopian carcinoma cells may not occur." (PMID 26633537, 2015). "Furthermore, AZD8797 was described as an allosteric inhibitor of CX3CR1; however, it is not known whether it leads to the same changes in the receptor conformation and affects the downstream signaling cascades in all tested ovarian cancer cell lines similarly." (PMID 39594684, 2024).
schizophrenia (16 papers, 2020 to 2023). A major psychotic disorder characterized by abnormalities in the perception or expression of reality. "Nevertheless, all of the observations shed a light and increasingly implicate the involvement of CX3CR1 and its ligand in mechanisms underlying schizophrenia." (PMID 34021899, 2021). "With this approach, it will be possible to manipulate disease-associated microglial genes in iPSC-MG, such as mutated C-X3-C motif chemokine receptor 1 (CX3CR1) in schizophrenia and autism spectrum disorder and mutated CSF1R in hereditary diffuse leukoencephalopathy with spheroid (HDLS)." (PMID 35910250, 2022). "But iMG subtype expressing ApoE, Ccr2, CD18, CD44, and CD95, as well as iMG subtype expressing IRF8, P2Y12, CX3CR1, and HLA-DR were main subtypes in schizophrenia." (PMID 36873215, 2023). "It is also interesting to note that CX3CR1, a chemokine receptor important in the recruitment of immune cells to sites of infection or auto-immunity, is decreased in schizophrenia and this is expressed on the endothelial side of the blood brain barrier (BBB)." (PMID 37850104, 2023). "Further suggesting a deficiency in microglia-neuron communication in schizophrenia models, a study demonstrated a disruption in the CX3CL1 (fractalkine released by neurons)-CX3CR1 (fractalkine receptor expressed by microglia) axis in poly I:C animals." (PMID 36443303, 2022). "Experiments in a pharmacological model of schizophrenia-like cognitive deficits induced by repeated ketamine administration showed the effect of cannabidiol (CBD) on the Cx3cr1 transcript level." (PMID 34021899, 2021). "To date, only a few studies have evaluated the expression of CX3CL1 and CX3CR1 in patients with schizophrenia." (PMID 34021899, 2021). "Recently, several studies have examined the modulation of CX3CR1 on microglia in patients with schizophrenia." (PMID 33013335, 2020). "Ala55Thr, an allelic variant of CX3C chemokine receptor 1 (CX3CR1), has been significantly correlated with schizophrenia while microglia are the only resource expressing CX3CR1 in the brain, point to the significance of these cells and their attendant functions." (PMID 36873215, 2023). "Support for the role of the CX3CL1-CX3CR1 pathway in psychiatric disorders comes from a meta-analysis of microarray data demonstrating a significant decrease in CX3CR1 expression in the postmortem brain and blood of individuals with schizophrenia." (PMID 33557113, 2021). "To investigate the effects of CX3CR1 on the schizophrenia-like behaviors induced by social isolation, we assessed the CX3CR1 protein levels within several regions, including the mPFC, NAc, and HIP, which are well-established sites for schizophrenia-like behavior." (PMID 33013335, 2020). "Our study first used an animal model of schizophrenia to demonstrate that CX3CR1 might be a necessary factor in the development of schizophrenia-like behaviors, and the blockade of CX3CR1 might be useful in treating schizophrenia." (PMID 33013335, 2020). "Also the reduced expression of CX3CR1 in schizophrenia could be the result of exhaustion due to an imbalanced immune response." (PMID 37850104, 2023). "Thus, the present study aimed to determine whether microglial CX3CR1 plays a role in schizophrenia-related behaviors." (PMID 33013335, 2020). "Thus, in this study, we aimed to test whether CX3CR1 plays a role in the social isolation-induced schizophrenia-like behaviors." (PMID 33013335, 2020). "Moreover, the CX3CR1 level was up-regulated in the medial prefrontal cortex, hippocampus and nucleus accumbens of the isolated wild-type mice, suggesting that the receptor might participate in the examined schizophrenia-like behaviors." (PMID 34021899, 2021). "In the same study, no discrepancies between control subjects and those affected by schizophrenia were found in terms of the transcript expression of neither CX3CL1 nor CX3CR1 in the orbitofrontal cortex." (PMID 34021899, 2021).
schizophrenia (continued). "The additional acute challenge with LPS later in life, according to the “two-hit” hypothesis of schizophrenia, decreased levels of hippocampal CX3CL1 in rats with altered PPI and cortical CX3CR1 in animals without such behavioral deficiency." (PMID 34021899, 2021). "To the best of our knowledge, this is the first study to determine the effects of CX3CR1 in an animal model of PPI-related schizophrenia-like behaviors, and we could not compare the results with related animal studies." (PMID 33013335, 2020). "However, until now, there has been a lack of research work to observe schizophrenia-like behaviors, such as prepulse inhibition (PPI), in CX3CR1−/− mice." (PMID 33013335, 2020).